IL1B (interleukin 1 beta)
Diseases named in the same sentence as IL1B in open-access papers (continued):
Sharing a sentence is not in itself a finding about the gene and the disease.
breast cancer (continued). "In breast cancer, researchers found that C5aR1-positive neutrophils secrete IL-1-β and TNF-α and they cooperatively activate ERK1/2 signal and phosphorylate WTAP at serine 341 to stabilize WTAP protein." (PMID 35251177, 2022). "The transcriptional upregulation of IL-1β is thought to be related to the occurrence of tumors, including lung, colon, and breast cancers, and it is also related with poorer prognosis." (PMID 36680047, 2022). "A reduced responsiveness to stimulation of peripheral monocytes observed in TC patients is in line with earlier findings in breast cancer patients, showing an impaired production of IL-1β, IL-6 and TNFα in response to LPS35,36." (PMID 36257966, 2022). "While Irena Kaplanov also demonstrated that blocking IL-1β facilitates immunosuppression in the TME of first-generation orthotropic mammary cancers." (PMID 36119049, 2022). "Then, after being exposed to DHA, breast cancer cells secreted more IL-1β and moved HMGB1 from the nucleus to the cytoplasm via activating caspase-1 and GSDMD." (PMID 36119049, 2022). "In our study, the level of IL-1β is elevated at all stages of breast cancer, particularly in the presence of even a single metastasis in the lymph nodes." (PMID 36286034, 2022). "In this study, we showed that IL-1β production in breast cancers is driven by NLRP3 activation in myeloid cells at disease baseline." (PMID 35631400, 2022). "Above all, this research presents an effective way of utilizing embelin and IL-1β-stimulated hUCMSCs in cancer therapy of different TRAIL-resistant breast cancer cells." (PMID 34282169, 2021). "In the lung metastasis of breast cancer, IL-1α and IL-1β secreted by breast cancer cells induce the production of CXCL9 and CXCL10 in lung fibroblasts through NF-κB signal transduction, thus promoting the growth of lung metastasis." (PMID 33722297, 2021). "The inflammatory cytokine IL-1β positively regulates mammary tumor growth and invasiveness by affecting the nature of myeloid cells and promoting TAM differentiation." (PMID 34064909, 2021). "Blocking IL-1β reverses the immunosuppression in mouse breast cancer and promotes tumor cell regression." (PMID 34805183, 2021). "We have previously shown that production of the pro-inflammatory cytokine interleukin-1B (IL-1B) by breast cancer cells drives bone metastasis in patients and in preclinical in vivo models." (PMID 34290237, 2021). "A high level of CCL2 in primary mammary tumor tissue is the major initiator of the tumor inflammation state via recruitment of inflammatory monocytes and release of IL-1β." (PMID 34386431, 2021). "For example, the interaction of LMW-HA with CD44 and TLR enhanced the production of IL-1β/IL-8 via the subsequent activation of MyD88/NF-κB and finally promoted the invasiveness of breast cancer cells." (PMID 33986244, 2021). "In vivo, inhibition of IL-1β signaling with either a mouse anti-IL-1ß -antibody (2 mg/kg) or the human anti-IL-1β antibody anakinra (1 mg/kg/day) reduced breast cancer bone colonization in hind limbs of mice." (PMID 33809315, 2021). "The pro-inflammatory cytokines tumor necrosis factor α (TNFα) and interleukin 1β (IL-1β) are expressed simultaneously and have tumor-promoting roles in breast cancer." (PMID 33806906, 2021). "The transwell co-culture system was used to confirm the apoptosis rate of embelin-treated breast cancer cells and IL-1β-stimulated hUCMSCs." (PMID 34282169, 2021). "In mouse models of breast cancer bone metastasis elevated expression of IL-1β has been determined in CTCs when compared to breast cancer cells isolated from mammary tumors." (PMID 33809315, 2021). "In breast cancer, the proinflammatory and prometastatic cytokines TNFα and IL-1β are present in tumors together, from the time of malignant transformation and on, throughout the process of cancer progression." (PMID 34072893, 2021).
breast cancer (continued). "Co-cultured embelin-treated breast cancer cells and IL-1β-stimulated hUCMSCs exert a synergistic effect in increasing TRAIL-mediated apoptosis." (PMID 34282169, 2021). "In view of these observations, in this study we determined the impact of continuous proinflammatory stimulation by both TNFα + IL-1β together on the malignancy phenotype of breast cancer cells." (PMID 34072893, 2021). "In three breast cancer cell lines, the group of co-cultured embelin-treated breast cancer cells and IL-1β induced hUCMSCs, enhanced nearly 40% of apoptotic cells including early apoptosis and late apoptosis." (PMID 34282169, 2021). "Major cellular sources for IL-1β secretion are antigen-presenting cells, but endogenous expression of IL-1β in breast cancer cells also increased metastatic potential, which was correlated with bone metastasis in breast cancer patients." (PMID 33686176, 2021). "Curtis TCGA data mining inversely correlated expression levels of oncostatin M (OSM), IL-6, and IL-1β with breast cancer patient survival." (PMID 35008370, 2021). "Interleukin-1 beta (IL-1β) is an active pro-inflammatory cytokine and elevated in many tumor types, including breast cancer." (PMID 34055597, 2021). "IL-1β is upregulated in many types of cancers, including breast cancer, suggesting its potential role in facilitating tumorigenesis." (PMID 34055597, 2021). "Pparγ1+/+ ErbB2 mammary tumors showed increased expression of specific chemokines and cytokines (Cxcl5, Cxcl19, Cxcl13, IL1b and Tnfrsf13c)." (PMID 33946495, 2021). "More p-c-Fos and p-c-Jun were accumulated on the nuclei of both breast cancer cells after IL-1β treatment, compared with the untreated control breast cancer cells indicating upregulated p-c-Fos and p-c-Jun." (PMID 34055597, 2021). "The results from 2 to 4 h of Matrigel-based cord formation assay also showed an increase in the number of intersections in breast cancer cells treated with IL-1β compared with the control stimulations." (PMID 34055597, 2021). "Together, these data suggest that microenvironment-derived IL-1B promotes breast cancer bone metastasis in vivo." (PMID 34290237, 2021). "Patients with estrogen receptor (ER)α-positive breast cancer were responsive to tamoxifen, but IL-1β diminished its chemotherapeutic efficacy by down-regulating ERα expression." (PMID 33686176, 2021). "The role of IL-1β during the pathogenesis of breast cancer appears to be similarly context-specific." (PMID 33946741, 2021). "For example, the activation of the NLRP3 inflammasome in CAFs and the subsequent IL-1β secretion promotes progression and lung metastasis of breast cancer." (PMID 34063828, 2021). "Human full-length IL1β-mRNA with Poly(A) was more detected as an unpacked vesicular form than packing form in EVs in breast cancer-derived TCM." (PMID 34135341, 2021). "The soluble TRAIL secreted from IL-1β-stimulated hUCMSCs effectively increased cell apoptosis in embelin-treated breast cancer cell lines." (PMID 34282169, 2021). "Our previous work suggests that IL-1B drives breast cancer metastasis in humanised models by inducing EMT at the primary tumour." (PMID 34290237, 2021). "We recently identified the pro-inflammatory cytokine Interleukin-1B (IL-1B) as a marker of breast cancer bone metastasis and showed that pharmacological targeting of IL-1B or its receptor (IL1R1) impairs bone metastasis." (PMID 34290237, 2021).
breast cancer (continued). "Here, we review and discuss the role of the best-validated ILs (IL-1β, IL-6, IL-8 and IL-11) involved in the bone cell—breast cancer cell crosstalk during the early events of breast cancer bone metastasis." (PMID 33809315, 2021). "In three breast cancer cell lines, the apoptotic rate was similar in breast cancer cells only, breast cancer cells co-cultured with hUCMSCs and breast cancer cells co-cultured with IL-1β-stimulated hUCMSCs groups." (PMID 34282169, 2021). "A similar function for IL-1A and IL-1B has also been reported: IL-1A and IL-1B produced by breast cancer cells can display the same function by equally activating IL1R1 in lung fibroblasts, which support metastatic colonisation." (PMID 34290237, 2021). "Elevated apoptotic cell population was found in embelin-treated breast cancer cells co-cultured with IL-1β-stimulated hUCMSCs and the apoptotic rate was nearly 30% in MDA-MB-231 cell line, and 40% in MCF-7 and MDA-MB-453 cell lines." (PMID 34282169, 2021). "Herein, we show that microenvironment-derived IL-1B has opposite function at different sites: IL-1B supports the development of breast cancer bone metastasis, whilst also reducing tumour growth at the primary site." (PMID 34290237, 2021). "Nevertheless, high FRH (41 °C) decreases the IL-1β mRNA level, and it surprisingly increases the level of IL-6 mRNA in ME-treated 4T1 breast cancer cells." (PMID 34201348, 2021). "Co-culturing embelin-treated breast cancer cells with hUCMSCs or with IL-1β-stimulated hUCMSCs led to more apoptotic cells than co-culturing untreated breast cancer cells with hUCMSCs or with IL-1β-stimulated hUCMSCs in all three cell lines." (PMID 34282169, 2021). "In the context of breast cancer, it has been demonstrated that IL-1β and NLRP3 were overexpressed in the breast tumor microenvironment concomitantly to the accumulation of MDSCs and TAMs." (PMID 33840390, 2021). "In these three breast cancer cell lines, the numerical value of CI was less than one, which indicates synergism in the combinations of embelin and IL-1β-stimulated hUCMSCs in increasing breast cancer cell apoptosis (CI < 1)." (PMID 34282169, 2021). "The research provides an anti-angiogenic therapeutic strategy to reduce the malignancy of breast cancer cells by targeting the VM promoted by IL-1β." (PMID 34055597, 2021). "In the TCGA data, among breast cancer, colon cancer, liver cancer, lung cancer, stomach cancer, and thyroid cancer, IL-1β expression was elevated in cancer tissues compared with that in matched normal tissues only in the colon." (PMID 33980323, 2021). "Metastatic breast cancer cells educate fibroblasts in lung metastases by secreting interleukin-1 alpha (IL-1α) and interleukin-1 beta (IL-1β), which trigger nuclear factor‐κB (NF-κB) signaling in MAFs." (PMID 34112258, 2021). "Although we found that 10 μg/mL of ME triggered only a slight decrease in the cell viability of breast cancer cells, this dose of ME significantly affects IL-1β and IL-6 mRNA expression." (PMID 34201348, 2021). "VEGF, TNF-α, IL-1β, and IL-6 expression levels documented in breast cancer patients were increased in the biopsies tissues compared to normal tissues." (PMID 34572719, 2021). "Another study has shown that bone marrow-derived interleukin (IL)-1β promotes metastatic colonization of disseminated breast cancer cells in the bone by stimulating the NF-κB/CREB-Wnt pathway." (PMID 34831167, 2021).
breast cancer (continued). "It has been reported that S100A9 probably plays a key role in inflammation-related breast cancers and induces the expression of pro-inflammatory cytokines (IL-6, IL-8, and IL-1β), thus, its expression level can be used to diagnose breast cancer." (PMID 34490085, 2021). "IL-1β induces tamoxifen resistance in the breast cancer cell model via prompting of Twist1 that propels methylation in the promoter region of the ESR1 gene which in turn reduces the expression of Erα." (PMID 34220337, 2021). "In a recent study, it was found that fibroblasts sense DAMPs and, in response, activates the NLRP3 pathway, resulting in a pro-inflammatory signaling and secretion of IL-1β in mouse and human breast carcinomas." (PMID 33840390, 2021). "qPCR analysis of c-Jun-bound chromatin confirmed that c-Jun binds to IL1A and IL1B promoters in breast cancer cells." (PMID 32198421, 2020). "In breast cancer, numerous studies have reported a pro-tumorigenic role of IL-1β, whereas blocking IL-1β reduces tumor growth." (PMID 33613533, 2020). "These adipocytokines affect cancer cell biology, and, for breast cancer, IL-1β overexpression in addition to leptin is reported to induce cancer cell colonization in BM." (PMID 32674405, 2020). "In contrast to most of the available data, metastasis-inhibiting effects have also been described for IL-1β in breast cancer." (PMID 33322216, 2020). "P73 and, more particularly, Tap73, a constitutively active p73, is able to increase the transcription of IL1B and CASP1 in lung and breast cancer cells, allowing these cells to produce IL-1β." (PMID 32635472, 2020). "Specifically, IL-1α and IL-1β secreted by breast cancer cells induce CXCL9 and CXCL10 production in lung fibroblasts via NF-κB signaling, fueling the growth of lung metastases." (PMID 32198421, 2020). "Using the cancer genome atlas (TCGA) database, breast cancer patients with high levels of mRNA expression of IL1B were shown to have a better prognosis than those with low levels." (PMID 32635472, 2020). "In a humanized model of spontaneous breast cancer metastasis to bone, production of IL-1β by cancer cells promotes EMT (altered E-Cadherin, N-Cadherin, and G-Catenin), invasion, migration, and bone colonization." (PMID 33123472, 2020). "In breast cancer metastasis, Schmid and colleague found that IL-1β was highly expressed in the microenvironment of murine lung, pancreatic, and breast tumors and was produced only by tumor-associated granulocytes and macrophage." (PMID 33322216, 2020). "Cytokine production is a central mechanism triggered by immune response against cancer, and high levels of systemic TNF-α and IL-1β has been reported in breast cancer patients." (PMID 32984049, 2020). "In breast cancer bone metastasis, it was suggested that IL-1β contributed to the osteotropic nature of breast cancer cells." (PMID 33322216, 2020). "In this regard, our and other previous studies have demonstrated that an estrogen-induced feedforward loop couples the IL-1β induction in CAFs to the IL1R1-stimulatory action elicited in breast cancer cells." (PMID 32778144, 2020). "Specifically, Sandra McAllister reported that IL-1β inflammatory response driven by primary breast cancer prevents metastasis-initiating cell colonization." (PMID 32123166, 2020). "In breast cancer, leptin upregulates all components of the IL-1 system (IL-1α, IL-1β, IL-1Ra and IL-1R tI) and both leptin and IL-1 together promote angiogenesis through expression of VEGF/VEGFR." (PMID 33339340, 2020).
breast cancer (continued). "We next sought to determine the relevance of IL-1β expression by gingival fibroblasts on breast cancer metastatic progression." (PMID 31685946, 2020). "In breast cancer, IL-1β induces BIRC3 expression and estrogen receptor (ER) α gene methylation, leading to EMT." (PMID 32635472, 2020). "Collectively, present results demonstrate a functional role of IL-1β signaling in migration and invasion of breast cancer." (PMID 33123472, 2020). "In agreement, an IL-1β/COX-2/PGE2 positive feedback was reported in breast cancer cells and macrophages." (PMID 32269145, 2020). "The NLRP3 inflammasome is the most extensively studied inflammasome, and activation contributes to immune system dysfunction and breast cancer metastasis by mediating the secretion of IL-1β." (PMID 32397236, 2020). "Blocking IL-1β reverts the immunosuppression in mouse breast cancer and enhances the activity of anti-PD-1 monoclonal antibodies." (PMID 32516941, 2020). "Inhibition of osteoprotegerin limits tumor invasion and metastasis, suggesting that osteoprotegerin and IL-1β play a role in mediating breast cancer metastasis." (PMID 33322216, 2020). "As it concerns IL-1β, its involvement in metastatic and angiogenic pathways toward breast cancer progression has been reported." (PMID 32778144, 2020). "Multiple inflammatory factors secreted by aggressive metastatic MDA‐MB‐231 breast cancer cells, including extremely high concentrations of IL1β, were able to induce NF‐κB signaling and secretion of inflammatory cytokines and chemokines in bystander cells." (PMID 31605433, 2020). "In mouse breast cancer, blocking IL‐1β reversed the immunosuppression and synergized with anti‐PD‐1 for tumor abrogation." (PMID 32508035, 2020). "Anakinra, a recombinant form IL-1 receptor antagonist, or canakinumab, an anti-IL-1B IgG1 antibody, decreased bone metastasis in a mouse model study of breast cancer bone metastasis." (PMID 32674405, 2020). "Monocytes from breast cancer patients secreted lower levels of IL-1β, IL-6, and TNF, while monocytes from renal cell carcinoma patients showed elevated production of these cytokines along with IL-10, CCL3, IL-8, and VEGFα." (PMID 33042791, 2020). "Mechanism research reveals that breast cancer cells are recruited to the human bone tissue by leptin and IL-1β derived from BMAs." (PMID 33123472, 2020). "We observed these processes in vitro when non-invasive MCF-7 breast cancer cells were treated with IL-1β, inducing an EMT program that changed the cells into an aggressive mesenchymal phenotype." (PMID 32244518, 2020). "Classical monocytes isolated from breast cancer patients also exhibit altered response to inflammatory stimuli, as indicated by their impaired secretion of TNFα and IL-1β in response to bacterial lipopolysaccharide." (PMID 33042791, 2020). "In this respect, IL-1β was involved in the connection between breast cancer cells and mesenchymal stem cells (MSCs), which are considered an additional source of CAFs beyond the fibroblasts." (PMID 32778144, 2020). "Pathogenic polymorphisms of other inflammatory genes like NRF2, IL1α, IL1β, IL6, IL8, and CXCR2 have also been identified in Tunisian and Egyptian breast cancer patients." (PMID 33659210, 2020). "Our findings here would help to further understand the role of IL1β signaling in breast cancer initiation and progression." (PMID 31921558, 2020). "Another study showed that breast cancer cells metastasize by inducing systemic inflammation, via IL-1β induction of IL-17 secretion from (γδ) T cells in a mouse model." (PMID 32784928, 2020).